GSDMD (gasdermin D)
Diseases named in the same sentence as GSDMD in open-access papers (continued):
Sharing a sentence is not in itself a finding about the gene and the disease.
lung cancer (28 papers, 2021 to 2025). A malignant neoplasm involving the lung. "demonstrate that mixed‐lineage leukemia 4 ablation decreases the expression of DNA methytransferases and RNA‐induced silencing complex, which causes GSDMD‐dependent pyroptosis and transcriptional reactivation of double‐stranded RNA for strengthened immunotherapy in human lung cancer (H1299) cells." (PMID 37125240, 2023). "In lung cancer, drugs induce pyroptosis by activating the caspase-1- GSDMD signaling pathway to inhibit tumor growth, though the specific mechanisms vary." (PMID 39994107, 2025). "These epigenetic modifications suppress NLRP3 expression, inhibit the activation of the NLRP3- caspase-1- GSDMD pathway, and confer an anti-pyroptotic phenotype to lung cancer cells." (PMID 39994107, 2025). "Being the downstream effectors in the inflammasome pathway, higher expression of GSDMD correlates with the pathophysiology of lung cancer, resulting in increased tumor size, advanced stages, and reduced survival rates in LUAD and LUSC patients." (PMID 41376623, 2025). "GSDMD is a crucial factor of pyroptosis and overexpressed in non‐small cell lung cancer (NSCLC) cells, which is closely related to the larger tumor size and lymph nodes metastasis." (PMID 37125240, 2023). "GSDMD colocalizes with GzmB near immune synapses to ensure the best CTL response to lung cancer cells." (PMID 37752941, 2023). "Similar studies also demonstrated that GSDMD expression was significantly upregulated in other cancers such as lung cancer and glioma." (PMID 36763290, 2023). "Through the EGFR/AKT signalling pathway, GSDMD increases lung cancer proliferation as well as an unfavorable prognosis." (PMID 36120543, 2022). "It was reported that Gasdermin-D (GSDMD) was essential for effector CD8+ T cell to respond to lung cancer as well." (PMID 35154117, 2022). "GSDMD or gasdermin-E (GSDME) in human B leukemic cells can be activated by chimeric antigen receptor T cell-released granzyme B and activated GSDMD is required for an optimal cytotoxic T lymphocyte response to lung cancer cells." (PMID 35619176, 2022). "However, knocking down of GSDMD showed an increase in the levels of metalloproteinases that facilitated apoptosis in lung cancer cells." (PMID 41376623, 2025). "In lung cancer, GSDMD contributes to the killing effect of cytotoxic T lymphocytes on cancer." (PMID 40704967, 2025). "In lung cancer, GSDMD facilitates cytotoxic T lymphocytes to kill cancer cells." (PMID 40704967, 2025). "Compared with the control group, the GSDMD, CASP4 and CASP5 expression in PBMCs of lung cancer patients was significantly higher(P < 0.05)." (PMID 37194012, 2023). "In this study, we analyzed GSDMD and GSDME protein expression levels after treatment of lung cancer cells with myricetin." (PMID 36091790, 2022). "It is estimated that upregulated GSDMD expression might play a considerable role in the progression and treatment resistance of osteosarcoma, which was already observed in other carcinomas, including nonsmall cell lung cancer, bladder cancer, and breast cancer." (PMID 36209102, 2022). "The GSDMD family, especially GSDMC, GSDMD, and GSDME can be consider as potential markers for the diagnosis and prognosis of lung cancer patients, including NSCLC." (PMID 36523974, 2022). "Furthermore, GSDMD was found to colocalize with GzmB near immune synapses and was essential for an optimal response of CTL to lung cancer cells." (PMID 36523974, 2022).
lung cancer (continued). "The level of GSDMD cleavage was increased in human activated CD8+ T cells, whereas GSDMD gene depletion decreased the cytolytic capacity of CD8+ T cells; thus, GSDMD was required to facilitate an optimal cytotoxic T-lymphocyte response to lung cancer cells." (PMID 34858408, 2021). "The level of GSDMD protein in lung cancer was significantly upregulated, and the expression of GSDMD was not correlated with age, gender, and lymph node metastasis in patients with LUAD; high expression of GSDMD was significantly correlated with tumor size and later TNM staging in LUAD patients." (PMID 36523974, 2022). "Knocking down BNIP3 with transfection reagent, then we extracted proteins and detected GSDMD and caspase-8 by western blot, and the results showed that knocking down BNIP3 increased GSDMD and caspase-8, indicating that knocking down BNIP3 could induce pyroptosis in lung cancer cells H358." (PMID 36092153, 2022).
viral infection (28 papers, 2019 to 2026). "In conclusion, our findings suggest that GSDMD‐CT attenuates the activation of IFN‐I immune signaling during virus infection." (PMID 40539222, 2025). "Pyroptosis is an inflammatory type of programmed cell death that mainly depends on the function of GSDMD in mammals and plays a crucial role in the pathogenesis of viral infection, whereas the mechanism of pyroptosis in chicken remains elusive." (PMID 39576037, 2025). "To investigate the roles of GSDMD during virus infection in vivo, we infected wild‐type (WT) and GSDMD‐knock‐out (GSDMD‐KO) mice with EMCV by intraperitoneal injection." (PMID 40539222, 2025). "GSDMD‐CT negatively regulates IFN‐I signaling during viral infection by triggering autophagic degradation of RIG‐I and TBK1." (PMID 40539222, 2025). "We scrutinized the expression of several representative genes associated with the response to virus and immune response, indicating that the expression of GSDMD‐CT dampened the immune response upon virus infection." (PMID 40539222, 2025). "Investigating the crucial amino acid sites of GSDMD‐CT that affect its inhibitory function on the type I IFN signaling pathway offers the potential for controlling viral infections." (PMID 40539222, 2025). "This study demonstrates that GSDMD‐CT acts as a negative regulator that suppresses IFN‐I signaling during viral infection." (PMID 40539222, 2025). "Immunofluorescence assays revealed that in neutrophils from WT mice, STING and GSDMD were colocalized on the membrane after viral infection, whereas in neutrophils from STING-KO mice, GSDMD expression was decreased after exposure to the virus." (PMID 40666504, 2025). "Although we have not been able to detect Mpro-mediated fragments of endogenous GSDMD in virus-infected cells, these results suggests that Mpro is capable of cleaving GSDMD in the context of virus infection." (PMID 38932190, 2024). "Notwithstanding, the function of GSDMD in virus infections remains obscure, despite extensive research into its regulatory functions within the inflammasome framework in response to cytosolic bacteria or LPS activation." (PMID 38584157, 2024). "Despite GSDMD inactivation during virus infection, we showed that HCoV-229E-infected cells still undergo lytic cell death." (PMID 38932190, 2024). "As we observed lytic cell death in HCoV-229E-infected cells, we next aimed at studying the status of the pyroptotic executioner GSDMD in the context of virus infection." (PMID 38932190, 2024). "We demonstrated that viral infection induces cleavage of GSDMD by increasing cleaved caspase-1 levels, and AZ has been shown to inhibit this process." (PMID 38247540, 2024). "Given its role as a driver of inflammation and pyroptosis, the role of GSDMD in driving inflammation during viral infection in vivo warrants further investigations." (PMID 38553499, 2024). "GSDMD has been found to be involved in several viral infections, with it able to restrict the progress of infection." (PMID 38002346, 2023). "While the essential roles of GSDMD in bacterial infection and cancer have been widely investigated, the importance of GSDMD in virus infection, including coronaviruses, remains elusive." (PMID 34899666, 2021). "By and large, the interaction effect of GSDMD activity and virus infection is complicated, which remains to be further elucidated." (PMID 34899666, 2021). "Here, we review the current literature regarding the activation and functions of GSDMD during virus infections." (PMID 34899666, 2021). "Furthermore, we observed a positive correlation between the mRNA transcription levels of NLRP3, caspase-1, and GSDMD and the duration of viral infection." (PMID 40284982, 2025). "In conclusion, our results demonstrate that GSDMD‐CT inhibits host defense against viral infection." (PMID 40539222, 2025). "We further found that under virus infection conditions, endogenous GSDMD‐CT, cleaved from GSDMD, could interact strongly with RIG‐I and TBK1." (PMID 40539222, 2025).
viral infection (continued). "Our investigations highlight the biological function of GSDMD‐CT and provide insight into potential strategies for viruses to activate pyroptosis and hijack host immune response components, thereby shedding light on virus infection control." (PMID 40539222, 2025). "In addition, PEDV nsp5 can sustain virus infection by suppression pyroptosis via pyroptosis by cleaving gasdermin D." (PMID 38289117, 2024). "By doing so, we hypothesized that if cleavage of GSDMD would occur during virus infection, resulting GSDMD fragments would be more easily detected by immunoblotting analysis." (PMID 38932190, 2024). "Therefore, to further explore the role of gasdermins in the context of viral infection, the virus-induced lytic cell death and IL-1β release were assessed in cells silenced for GSDMD and GSDME expression using siRNA." (PMID 37680489, 2023). "In addition to bacteria and virus infection, the role of GSDMD has also been proposed during fungal infection." (PMID 35774778, 2022). "Given the critical roles of the IFN-elicited ISG response against virus infection, we hypothesized that GSDMD suppresses TGEV infection by enhancing the IFN-mediated antiviral ISG responses induced by TGEV infection." (PMID 35100869, 2021). "It is unknown whether GSDMD serves protective or detrimental functions for virus infection, including coronavirus infection." (PMID 35100869, 2021). "Moreover, we showed that pyroptosis also occurs during viral infection, as inferred from the increase in Gasdermin D mRNA levels in both infected lung and brainstem cultures." (PMID 34608167, 2021). "While the substantial importance of GSDMD in microbial infection and cancer has been widely investigated, the role of GSDMD in virus infection, including coronaviruses, remains unclear." (PMID 35100869, 2021). "While the functions and importance of GSDMD as a regulator of inflammasome activities in response to cytosolic bacterial infection or LPS stimulation have been extensively investigated, the roles of GSDMD during virus infection remain unclear." (PMID 34899666, 2021). "Our study identifies GSDMD‐CT as a negative regulator in antiviral innate immunity and offers a perspective on the potential for viruses to activate pyroptosis to evade host antiviral response, thereby shedding light on virus infection control and disease therapy." (PMID 40539222, 2025). "Furthermore, our in vitro experiments demonstrated that STING and GSDMD colocalized to the membrane of neutrophils isolated from WT mice after virus stimulation, but that the membrane expression of GSDMD was reduced in neutrophils isolated from STING-KO mice following viral infection." (PMID 40666504, 2025). "However, whether GSDMD regulates orchitis pathogenesis in response to other bacterial and viral infections remains unclear, which also warrants further investigation." (PMID 38177538, 2024). "Studies on pharmacological inhibition of various viral diseases have shown that inhibition of Caspase-1 could block the GSDMD-mediated cell pyroptosis process and reduce the expression levels of IL-1β and IL-18, leading to corresponding therapeutic effects on viral diseases." (PMID 38132483, 2023). "Moreover, NLRP3 activation can lead to pyroptosis, an inflammatory programmed cell death pathway activated through Gasdermin D (GSDMD) cleavage by caspase 1, 4, 5, and/or 11 that takes place in T lymphocytes and is crucial in the pathogenetic process associated to viral infections." (PMID 35336077, 2022). "Viral infection of M1 macrophages upregulated the mRNA levels of NLRP3, caspase-1, and Gasdermin D (GSDMD)." (PMID 41305513, 2025). "The GSDMD, PAD4 and PAD2 expression levels exhibited an increasing trend with increasing virus infection time." (PMID 40666504, 2025). "Upon reconstitution with GSDMD‐FL‐WT, the cells exhibited decreased mRNA levels of IFNB and Isg54 upon viral infection, correlating with the presence of cleavage fragments." (PMID 40539222, 2025).
viral infection (continued). "The gasdermin D (GSDMD) is the most studied executioner of pyroptosis, which plays a crucial role in virus infections (49, –, 51)." (PMID 39982110, 2025). "In this study, we reported that the heightened ROS induced by viral infection activates the NLRP3 inflammasome, leading to GSDMD activation." (PMID 38247540, 2024). "Further investigations of the roles of GSDMD in releasing the IFN-I in various cells and virus infection will help us better understand the host’s finely tuned IFN-I response in the context of virus infection." (PMID 35100869, 2021). "It is not surprising that GSDMD as a primary effector of pyroptosis involves viral infection pathogenesis." (PMID 34899666, 2021). "At the same time, we found that CT26 and CMT93 VT also exhibited natural hyperactivation of GSDMD, GSDME, and p-MLKL, because they were constructed by cas9-expressing lentiviral vector, they could induce natural hyperactivation of GSDMD, GSDME, and p-MLKL through viral infection." (PMID 38740747, 2024). "However, unlike in viral infection, deletion of ZBP1 in our fungal model did not result in a complete loss of CASP1 activation, GSDMD cleavage, or apoptotic protein (CASP8, CASP3, and CASP7) activation." (PMID 33109609, 2020). "Considering the negative impact of GSDMD‐CT on IFN‐I signaling, identifying the specific amino acid sites that mediate this function is crucial, as it may offer avenues for controlling viral infections and developing therapeutic strategies." (PMID 40539222, 2025).
colorectal cancer (27 papers, 2019 to 2025). A primary or metastatic malignant neoplasm that affects the colon or rectum. "Specifically, nuclear localization of GSDMD is associated with favorable clinical outcomes in colorectal cancer." (PMID 40783818, 2025). "Our recent studies have uncovered the function and mechanism of GSDMD‐induced pyroptosis during intestinal inflammation and its associated colorectal cancer." (PMID 38982510, 2024). "To date, GSDMB and GSDMD have been shown to accumulate in the nucleus of human bronchial epithelial cells and colorectal cancer cells, respectively." (PMID 40783818, 2025). "In colorectal cancer cells, GSDMD regulates its subcellular distribution from the cytoplasm to the nucleus where it interacts with the ADP‐ribosylation factor PARP‐1 [Poly (ADP‐ribose) polymerase 1] to dramatically inhibit its DNA damage repair function." (PMID 40783818, 2025). "High intratumoral expression of GSDMD has been associated with poor prognosis in hepatocellular carcinoma, but this protein was found to be downregulated in colorectal cancer (CRC), and GSDMD deficiency enhanced the development of CRC in mice." (PMID 39224600, 2024). "Surprisingly, GSDMD‐induced pyroptosis following drug administration has rarely been observed in colorectal carcinoma cell lines." (PMID 38804602, 2024). "Subsequently, a multivalent CXCR4-targeted nanotoxin was developed to induce GSDMD-mediated pyroptosis and inhibit colorectal cancer progression." (PMID 38066523, 2023). "Second, subcellular localization differences could critically modulate its activity—nuclear translocation of GSDMD has been shown to inhibit some malignant phenotypes of colorectal cancer." (PMID 40491921, 2025). "We hypothesize that ESCRT actively removes GSDMD pores in colorectal cancer cells to prevent their cell death, thus allowing the tumor-promoting function of GSDMD." (PMID 38898209, 2024). "Additionally, LINC00365 was confirmed to be positively correlated with miR-221-5p, and miR-221-5p is negatively correlated with gasdermin-D (GSDMD) in colorectal cancer tissues." (PMID 39439418, 2024). "Therefore, we proposethat IL-17A activates the NF-κB pathway, triggering the activation of caspase-4 and the cleavage of GSDMD in colorectal cancer cells." (PMID 37211606, 2023). "To examine the expression pattern of GSDMD in the TME, we performed immunofluorescence with tumor specimens from colorectal cancer and pancreatic adenocarcinoma patients." (PMID 40759573, 2025). "Colorectal cancer (CRC) cells, on the other hand, have reduced GSDMD protein levels, which can inhibit the occurrence of CRC by activating GSDMD." (PMID 38228635, 2024). "Importantly, GSDMD activation in intratumoral CD4+ T lymphocytes correlates with survival benefit and immunotherapy efficacy in colorectal cancer and pancreatic adenocarcinoma." (PMID 40759573, 2025). "In colorectal cancer, GSDME might be a positive regulator in cell invasion and metastasis through cell migration and angiogenesis, while GSDMA, GSDMB and GSDMD might be a negatively regulator of cell migration." (PMID 35164740, 2022). "Though our analysis, we found that GSDMA, GSDMB, GSDMD and GSDME might be involved in colorectal cancer cell invasion and metastasis, and the former three might played as negative regulators while the last one played as a positive regulator." (PMID 35164740, 2022). "The colorectal cancer cell line HCT116 was chosen because it expresses high levels of GSDME but not GSDMD." (PMID 32332857, 2020). "Colon-26 murine colorectal carcinoma cells, which express GSDMD but not ASC, were stably transfected with Fv3-mCasp1 (CL26-iCasp1 cells) or Fv3-mCasp8 (CL26-iCasp8 cells)." (PMID 31064994, 2019).
colorectal cancer (continued). "Interestingly, nuclear GSDMD, as opposed to its cytoplasmic counterpart, has been found to suppress the growth of colorectal cancer cells by inducing apoptosis under chemotherapy stimulation rather than through pyroptosis-mediated cell death." (PMID 38066523, 2023). "It has been shown in colorectal cancer that NLRP3 activation can enhance antitumor immunity by promoting NK cell activity and IL-18/IFN-γ signaling, whereas microbiota-driven dysregulation of NLRP3/GSDMD may instead support tumorigenesis through disrupted signaling." (PMID 41291696, 2025).